SOD2 (superoxide dismutase 2)
Diseases named in the same sentence as SOD2 in open-access papers (continued):
Sharing a sentence is not in itself a finding about the gene and the disease.
breast carcinoma (continued). "With regard to lnc-MAFG-AS1, it exhibits tumorigenesis by regulating the miR-574/SOD2 axis in breast cancer; it also reverses miR-34a maturation to induce glioblastoma growth; besides, it accelerates pancreatic cancer progression by binding miR-3196 to outburst NFIX." (PMID 36034393, 2022). "In addition, tirchostatin A and sodium butyrate were also found to alter SOD2 expression by regulating histone methylation and acetylation in breast cancer cells." (PMID 35164076, 2022). "The measurements of circulating SOD2 in plasma could improve the non-invasive monitoring of the therapeutic treatment in breast cancer patients." (PMID 36010852, 2022). "As expected, both PPARα and SOD2 were significantly downregulated in breast cancer." (PMID 35534547, 2022). "SIRT3 and SOD2 are decreased in the breast carcinoma cells with activated UPRmt." (PMID 34717757, 2021). "In addition, a breast cancer study demonstrated that there was a positive correlation between SOD2 and EMT in breast cancer cells." (PMID 33535682, 2021). "Moreover, the superoxide scavenging enzyme SOD2 (superoxide dismutase 2), found overexpressed both in radioresistant breast cancer and ALL cells, at normal expression levels provides a cytoprotective effect." (PMID 33898418, 2021). "Concerning breast cancer, SOD2 expression levels are different in the various histotypes, being upregulated in both tissue specimens and cell lines derived from the more “aggressive” basal-like, claudin low-, and estrogen receptor-negative subtype, including MDA-MB231." (PMID 30934784, 2019). "Furthermore, the activity of SOD2 was decreased to 87% of breast cancer cases, whereas the levels of SOD1 and ROS were upregulated." (PMID 30279365, 2018). "Furthermore, the expression ratio of SOD1/SOD2 seems to be a switch and plays an essential physiological role in breast cancer cells." (PMID 30279365, 2018). "Similarly, accumulating evidence suggests that SOD2 expression is correlated with chemoresistance in lymphoma, basal-like breast carcinoma, and lung adenocarcinoma." (PMID 28947972, 2017). "However, the expression of SOD2 in malignancies of different tissue origin varies significantly, from down-regulation in esophageal, pancreatic and breast cancer, to elevated level in ovarian, gastric and colorectal cancer." (PMID 27221200, 2016). "In another study, patients with breast cancer and the high-activity genotype Ala/Ala in the SOD2 rs4880 SNP who were treated with regimens containing cyclophosphamide, but not with hormonal regimens, had significantly poorer prospects for survival than patients with low activity Val alleles." (PMID 24348785, 2014). "The SOD2 locus is adjacent to chromosomal regions that are frequently deleted in breast cancer." (PMID 24498107, 2014). "In addition to SIRT3, we recently reported that SOD2 itself is down-regulated in breast cancer cell lines upon activation of oncogenes, such as Ras." (PMID 24955214, 2014). "They suggest little evidence of an association between a polymorphism in SOD2 and breast cancer outcomes among women treated with adjuvant chemotherapy." (PMID 24498107, 2014). "BCAC also analyzed data from 12 studies for 16 SNPs in various candidate genes and concluded that only 5 SNPS (CASP8 D302H, IGFBP3-202 c > a, PGRV660L, SOD2 V16A, and TGFB1 L10P) were associated with breast cancer, but the statistical significance of the association was only borderline." (PMID 21655367, 2008). "Moreover, the SOD2 rs4880 AG genotype was associated with non-chemotherapy response in breast cancer patients." (PMID 40565143, 2025). "Furthermore, miR‐335 negatively regulated SOD2 expression in breast cancer cells." (PMID 37909239, 2023). "Therefore, the measurement of SOD2 levels in plasma could improve the non-invasive monitoring of the therapeutic treatment in breast cancer patients." (PMID 36010852, 2022).
breast carcinoma (continued). "In another study, the analysis of human breast cancer datasets revealed that the expression of caveolin-1 (CAV-1) was inversely correlated to that of NRF2 or superoxide dismutase-2 (SOD-2), and this could predict the development of more aggressive forms of cancer." (PMID 33805996, 2021). "Furthermore, by using a mouse model of genetically induced breast cancer, the reduced expression of CAV-1, associated with elevated SOD-2 and enhanced AMPK activation, was also confirmed in tissue sections from mammary tumors but not in their healthy counterparts." (PMID 33805996, 2021). "Therefore, the role of antioxidants in breast cancer is often controversial; for example antioxidant superoxide dismutase 2 (SOD2), which converts the highly toxic radical superoxide into more stable hydrogen peroxide in the mitochondria, can act both as an oncogene and as a tumor suppressor." (PMID 31627322, 2019). "Therefore, the switch mechanism of SOD1 to SOD2 may play a significant role in cellular physiology, such as invasion or proliferation of breast cancer cells." (PMID 30279365, 2018). "Additionally, in a collection of 50 matched primary and metastatic lesions from breast cancer patients, using SOD2 as a marker, we observed a significant increase in activation of the SIRT3 axis of the UPRmt, in metastatic lesions when compared with primary lesions." (PMID 28798902, 2017). "Association between MnSOD (SOD2) genotype and breast cancer recurrence among women who received cyclophosphamide-epirubicin-5-fluorouracil (CEF) adjuvant chemotherapy; women aged 35 to 69 years at breast cancer diagnosis who resided in Jutland, Denmark, 1991–2001." (PMID 24498107, 2014). "In addition, SOD2 overexpression suppresses the tumorigenicity of breast cancer cells." (PMID 22646717, 2012). "Our PCA analysis suggests that SOD2, KLK5, KLK7, and IL8 play a significant role in the worsening of breast cancer pathology." (PMID 40426890, 2025). "According to alcohol metabolism-involved genes, three were up-regulated (ITGA5, CBS, and SOD2), and six were down-regulated (XDH, XRCC1, MTHFR, CYP1B1, XPC, and GSTP1) among women who died for breast cancer." (PMID 39125744, 2024). "MDR analysis also showed a close interaction and mutual enhancement of effects between the APEX1 and SOD2 loci and the independence of the effects of these loci from the CAT locus in the formation of luminal B subtype breast cancer." (PMID 39027127, 2024). "Alateyah N., Gupta I., Rusyniak R.S., Ouhtit A. SOD2, a potential transcriptionaltarget underpinning CD44-promoted breast cancer progression.Molecules." (PMID 39027127, 2024). "It was found that the decrease of MnSOD expression in breast cancer cell lines was related to the deacetylation of H3K9 and hypomethylation of H3K4 on the seven transcriptional regulatory elements in SOD2." (PMID 37759978, 2023). "In the present study, we identified a ZNF‐148/miR‐335/SOD2 axis in breast cancer cells, and we demonstrated that ZNF‐148 represses miR‐335 and then increases SOD2 expression, consequently decreasing pyroptosis in a ROS‐dependent manner." (PMID 37909239, 2023). "In breast cancer cells, SOD2 to SOD1 switch is found, resulting in the SOD2 down-regulation, and SOD1 upregulation, and SOD1 functions to maintain the integrity of the organelle." (PMID 35978820, 2022). "We took one of them, manganese superoxide dismutase (MnSOD or SOD2), as a model protein for its validation as a candidate response biomarker for breast cancer neoadjuvant treatment." (PMID 36010852, 2022). "We selected manganese superoxide dismutase (SOD2), a mitochondrial redox enzyme, from a screening of proteolytic resistant proteins in breast cancer (BC)." (PMID 36010852, 2022). "This is interesting, as SOX2 transcription and SNAIL expression have been reported to be SOD2-sensitive, and SNAIL overexpression alone is sufficient to generate tumor-initiating breast cancer cells." (PMID 35326667, 2022).
breast carcinoma (continued). "Three genes were up-regulated (i.e., ITGA5, CBS, and SOD2), while six were down-regulated (i. e, XDH, XRCC1, MTHFR, CYP1B1, XPC, and GSTP1) among individuals who died of breast cancer." (PMID 32078659, 2020). "Another example is the activation of AMPK in response to the overexpression of manganese superoxide dismutase (MnSOD/SOD2) and consequential increases in mitochondrial H2O2 production in breast cancer cells." (PMID 32059571, 2020). "Upon cholesterol treatment, there is a significant increase in the expression of metabolic target genes of ERRα, including IDH3A, VEGF, PDK4, SOD2, GSTM1, and SPP1, in breast cancer cells." (PMID 32717915, 2020). "For example, in the colorectal cancer cell line LS-180, SOD activity was found to be upregulated, while in the breast cancer cell line SKBR3, SOD1 was found to be downregulated and SOD2 upregulated." (PMID 33086722, 2020). "The inverse correlation between SOD2 and DDB2 expression in breast cancer patient-derived samples further establishes DDB2 as a negative transcriptional regulator." (PMID 29099803, 2017). "The mitochondrial antioxidant enzyme, SOD2, was over-expressed in HCC1937 cells, whereas catalase was expressed at wild type level in both breast cancer cell lines." (PMID 17192190, 2006). "SOD2 has been demonstrated to be targeted by miR‐335,23 supporting our hypothesis that miR‐335 serves as a “bridge” to combine ZNF‐148 and SOD2 in breast cancer cells, and we demonstrated that a ZNF‐148/miR‐335/SOD2 pathway exists in breast cancer." (PMID 37909239, 2023). "Finally, we demonstrated that the miR‐335 mimic abrogated the promoting effects of ZNF‐148 overexpression in SOD2 in breast cancer cells, suggesting that miR‐335 is a link between ZNF‐148 and SOD2." (PMID 37909239, 2023). "It is thus significant that cholesterol binding to ERRα and cholesterol-mediated increase in ERRα-PGC-1α interaction result in increased expression of ERRα itself and its metabolic target genes including IDH3A, VEGF, SOD2, GSTM1, PDK4, SPP1 in breast cancer cells." (PMID 32717915, 2020). "We have further shown that miR-195 enhances mitochondrial SOD-2 expression but does not affect PINK1 levels in breast cancer cells." (PMID 30932749, 2019). "In general, more aggressive breast cancers (MDA-MB-231, SUM159PT, BCCL2, BCCL3) had lower levels of TMX1 and SOD1 relative to the luminal MCF-7 cells, and showed up-regulated expression of TMX3, Foxo1, GSS and SOD2." (PMID 22479642, 2012). "Here, we suggest that SOD2 is also non-classically secreted in breast cancer cells." (PMID 36010852, 2022). "The mitochondrial-targeted superoxide dismutase 2(SOD2) is a potential inhibitor that can resist to oxidative stress and block the production of molecules that can nourish tumors, thereby effectively reversing the tumor-promoting phenotype of CAV-1 in breast cancer cells." (PMID 33816265, 2021). "Because both miR‐335 and SOD2 are involved in regulating pyroptosis, we next explored whether ZNF‐148 modulates this progression through the miR‐335/SOD2 axis by transfecting the ZNF‐148 silencing vector, miR‐335 inhibitor, and SOD2 overexpression vector into breast cancer cells." (PMID 37909239, 2023). "Associations of polymorphisms in the hOGG1 (rs1052133), APEX1 (rs1130409), XPD (rs13181), SOD2 (rs4880), and CAT (rs1001179) genes were studied in 313 nonsmoking postmenopausal patients with luminal B subtype breast cancer." (PMID 39027127, 2024). "Upregulation of ZNF‐148 occupied miR‐335 in breast cancer cells, and the remaining miR‐335 was not sufficient to target the 3′‐UTR of SOD2 mRNA, resulting in SOD2 upregulation." (PMID 37909239, 2023).
breast carcinoma (continued). "The published breast cancer dataset (GSE48390) revealed a positive correlation between RUNX2, MTA1 and CUL4B, and negative correlations among RUNX2/MTA1/CUL4B and PPARα/SOD2." (PMID 35534547, 2022).
diabetes (153 papers, 2007 to 2026). "Recent studies have pointed out that rs4880 in the SOD2 mutation can lead to reduced Mn-SOD activity and is closely associated with diabetes, atherosclerosis, coronary heart disease, and tumorigenesis." (PMID 36759651, 2023). "Superoxide dismutase 2 (SOD2) polymorphisms have been implicated in several diseases including diabetes mellitus, Alzheimer’s disease, heart disease, and cancers; including breast and PCa." (PMID 33535682, 2021). "As clearly demonstrated in the logistic model adjusted for age and BMI, increased SOD2 levels lead to reduced risk of developing prediabetes and diabetes." (PMID 30803440, 2019). "Increased SOD2 reduced the risk of prediabetes [OR (95% CI) = 0.92 (0.86-0.98); p = 0.0066] and diabetes [OR (95% CI) = 0.7 (0.57–0.87); p = 0.0009]." (PMID 30803440, 2019). "Other studies had shown that a dysfunctional SOD2 is positively associated with cardiovascular disease risk, neurodegeneration, diabetes, and different forms of cancers." (PMID 28512644, 2017). "SOD2 upregulation is associated with the improvement of endothelial function in experimental models of diabetes, hypertension, and metabolic syndrome." (PMID 28713487, 2017). "The results indicated that the elevated ROS production levels caused by the reduced SOD2 mediated coronary endothelial dysfunction in diabetes." (PMID 29095915, 2017). "The presence of TT (Val/Val) genotype in SOD2 gene was associated with poorer diabetes control in comparison with CT (Ala/Val) and CC (Ala/Ala) genotypes." (PMID 18423055, 2008). "In rats with diabetes, transient hyperglycemia induces persistent reactive oxygen species (ROS) generation and oxidative stress-mediated histone methylation, further suppressing SOD2 expression, which was the major cause of ASD in rat offspring." (PMID 36479216, 2022). "On the contrary, Sod2 Val phenotype increases the risk of developing diabetes." (PMID 35204196, 2022). "Conversely, cardiomyocyte-specific overexpression of Sod2 provided protection against oxidative stress and improved mitochondrial respiration in a mouse model of diabetes." (PMID 40034852, 2025). "NLRP3/IL-6/IL-1/TNF-α expression was reduced, and diabetes/hyperglycaemia-induced oxidative stress was suppressed, as evidenced by decreased 8-isoprostane and elevated superoxide dismutase-2 levels in vitro and in vivo." (PMID 41214779, 2025). "The results revealed that the number of CSPCs decreased by 75–85% in mice with induced diabetes mellitus (DM) in the SOD-2+/− group, and the DM-SOD-2+/− group." (PMID 41155562, 2025). "The possibility of protein-level reductions in other antioxidant enzymes, such as SOD1, SOD2, and catalase, under diabetes distress remains to be explored and constitutes a major limitation of our study." (PMID 41462586, 2025). "Evidence of hippocampal oxidative damage was most marked in mice with STZ-diabetes exposed to post-hypoglycaemic hyperglycaemia; these mice also showed induction of Nrf2 and the Nrf2 transcriptional targets Sod2 and Hmox-1." (PMID 37015997, 2023). "The protein levels of SOD2 were upregulated in the hippocampus but significantly decreased in the cerebral cortex of STZ female animals by diabetes." (PMID 36674713, 2023). "AMPK activation has been reported to decrease mitochondrial ROS by upregulating SOD2 in a diabetes animal model." (PMID 37199590, 2023). "The overexpression of SOD2 in transgenic mice protects against the development of acellular retinal capillaries in diabetes." (PMID 37627644, 2023). "Next, we also evaluated the potential effect of HSCT and Sod2 expression on maternal diabetes–mediated inflammation in IECs." (PMID 35220596, 2022). "We evaluated the potential effect of HSCT and Sod2 expression on maternal diabetes–mediated oxidative stress in a mouse model." (PMID 35220596, 2022). "Next, we evaluated the potential effect of HSCT and SOD2 expression on maternal diabetes–mediated inflammation in PBMCs." (PMID 35220596, 2022).
diabetes (continued). "We first measured gene expression in amygdala tissues and found that maternal diabetes induction (STZ‐HSCT/STZ/EMP) significantly decreased the mRNA levels of Sod2, Esr2 (ERβ), and Syp compared with the control (CTL‐HSCT/CTL/EMP) group." (PMID 35220596, 2022). "We then evaluated the potential effect of HSCT and Sod2 expression on maternal diabetes–mediated oxidative stress in IECs." (PMID 35220596, 2022). "We found that maternal diabetes induction (STZ‐HSCT/STZ/EMP) significantly decreased mRNA levels of Sod2, Zo1, and Cldn1, compared with the control (CTL‐HSCT/CTL/EMP) group." (PMID 35220596, 2022). "The data showed that maternal diabetes induction (STZ‐HSCT/STZ/EMP) significantly decreased endogenous Sod2 expression, compared with the control (CTL‐HSCT/CTL/EMP) group." (PMID 35220596, 2022). "We then evaluated the potential effect of HSCT and Sod2 expression on maternal diabetes–mediated GI dysfunction." (PMID 35220596, 2022). "SOD2 activity was diminished in the diabetes group and showed a significant increase in the apocynin group." (PMID 33668280, 2021). "Quercetin reversed the effects of diabetes on SOD-2 and induced significant increase of SOD-2 levels in comparison to diabetic vehicle-treated hearts." (PMID 33923282, 2021). "Serum LDL-C levels also showed weak positive correlation with SOD2 (r = 0.113, p = 0.047), and type 2 diabetes mellitus showed moderate correlation with NOS2 (r = 0.397, p < 0.001)." (PMID 33924357, 2021). "The reduced SOD2 expression promotes oxidative stress and contributes to diabetes-related endothelial dysfunction." (PMID 33996829, 2021). "Accumulating evidence supports critical roles of SOD2 in the pathogenesis of various disorders, including diabetes, neurogenerative diseases, and skin aging, through the regulation of mtROS homoeostasis." (PMID 33634989, 2021). "Here, we found that similar SOD2 suppression occurred in both HSC and PBMC in maternal diabetes-induced autistic offspring due to inheritance of epigenetic changes on the SOD2 promoter." (PMID 33101089, 2020). "In this study, we demonstrated that maternal diabetes-induced mouse autistic offspring have epigenetic modifications and SOD2 suppression in both HSC and PBMC." (PMID 33101089, 2020). "We found that SOD2/ERβ expression was suppressed in PBMC in maternal diabetes-induced autistic offspring in the mouse model." (PMID 33101089, 2020). "This study has determined that maternal diabetes-induced mouse autistic offspring have epigenetic changes on the SOD2 promoter that result in SOD2 suppression in both HSC and PBMC." (PMID 33101089, 2020). "BMT of normal HSC to maternal diabetes-induced offspring reversed SOD2 suppression and elevated cytokine levels in PBMC." (PMID 33101089, 2020). "In our study, diabetes markedly resulted in down-regulation of Nrf2, HO-1 and SOD2, an effect that was reversed by FGF1 treatment." (PMID 32194395, 2020). "DHY attenuated MDA level, superoxide level, and ROS production, as well as mitochondrial superoxide level, but enhanced T-AOC activity, GSH/GSSG level, and SOD2 activity in the thoracic aorta of WT mice with diabetes." (PMID 32933152, 2020). "Nevertheless, there are contradictory findings in the literature regarding the levels of SOD2 in patients with diabetes." (PMID 30736780, 2019). "The finding that SOD2 was increased at the mRNA and protein levels in all groups suggests its role in counteracting the observed oxidative stress in diabetes and HT." (PMID 30736780, 2019). "Our results are in line with GENEDIAB study, where the SOD2 rs4880 polymorphism was associated with advanced oxidation protein products (AOPP) elevation and lower SOD2 activity, among 310 diabetes mellitus patients who developed diabetic nephropathy." (PMID 31340563, 2019). "We continued to evaluate the effect of maternal diabetes on autism-like behaviors with the manipulation of SOD2 expression." (PMID 31685635, 2019).